TRAJ47 (T cell receptor alpha joining 47)
Gene: T-cell receptor joining (J) gene on chromosome 14 (22,492,851 to 22,492,907, forward strand). Ensembl gene ENSG00000211842.
Diseases named in the same sentence as TRAJ47 in open-access papers:
TRAJ47 is named in the same sentence as 2 diseases in open-access papers, as found by Europe PMC text mining. Sharing a sentence is not in itself a finding about the gene and the disease. The quoted sentences say what the papers report.
cancer (1 paper, 2025). A tumor composed of atypical neoplastic, often pleomorphic cells that invade other tissues. "Of the remaining cancer-activated MR1-restricted TCRs, some used the MAIT cell–preferred TRAJ20 and TRAJ12 to generate a similarly placed tyrosine and others used TRAJ26, TRAJ47, or TRAJ32 to encode this tyrosine residue." (PMID 39744940, 2025).
TRAJ47 also shares sentences with these, for which no sentence is quoted: COVID-19 (1 paper).